E2F1 (E2F transcription factor 1)
Diseases named in the same sentence as E2F1 in open-access papers (continued):
Sharing a sentence is not in itself a finding about the gene and the disease.
infection (continued). "Having assessed the effect of API5 on E2F1-dependent transactivation of proapoptotic genes under conditions of infection, we next set out to investigate its impact on the process of apoptosis itself." (PMID 26673663, 2015). "In the present study, we elucidate how NP of IAV interact with and manipulate a host inhibitor of apoptosis API5 during infection, and in the process stimulating E2F1-dependent apoptotic pathway." (PMID 26673663, 2015). "Infected PBMCs with the wild-type virus were initially assessed for mRNA expression levels of both EBNA3C and E2F1 at different times of post-infection (0, 2, 4, 7 and 15 days)." (PMID 22438805, 2012). "We find that EBNA3C can prevent cells from entering E2F1-dependent apoptosis both at early and latent stage of infection and possibly that this effect is critically dependent on the specific interaction between the DNA binding domain of E2F1 and EBNA3C." (PMID 22438805, 2012). "This percentage dropped to ∼16% when either of two siRNAs targeting E2F1 expression was transfected into cells prior to infection." (PMID 21589897, 2011). "HEL fibroblasts were transfected with siRNAs specific for E2F1 or with a control siRNA 24 h prior to infection with HCMV." (PMID 21589897, 2011). "Expression-profiling of Toxoplasma-infected HFFs demonstrated that there are modest increases in the levels of E2F3 (+1.4-fold), c-Myc (+1.9-fold) and E2F1 (+1.5-fold) in Toxoplasma-infected HFFs relative to uninfected HFFs at 24h post-infection." (PMID 20090903, 2010). "We confirmed that, when miR-20a is over-expressed either by transient transfection or stable infection, E2F1 is invariably decreased." (PMID 18596985, 2008). "As expected, the PUMA promoter was activated 2.2-fold after Ad-E2F-1 infection in HCT116 PUMA+/+ cells." (PMID 17263886, 2007). "The increased PUMA protein expression corresponded with the up-regulation of PUMA mRNA after Ad-E2F-1 infection in this cell line." (PMID 17263886, 2007). "In HCT116 PUMA-/- cells, caspase-9 activity was also increased after Ad-E2F-1 infection, but to a lesser degree (1.5 fold after 48 hours of Ad-E2F-1 infection)." (PMID 17263886, 2007). "While loss of PUMA protected the HCT116 cells against E2F-1-induced cell death, the HCT116 PUMA-/- cells eventually underwent cell death after Ad-E2F-1 infection." (PMID 17263886, 2007). "Quantitative real-time PCR analysis showed that a 2.6-, 5-, and 10-fold increase of PUMA mRNA levels was observed in SK-MEL-2 cells after E2F-1 infection at 8 hours, 12 hours, and 16 hours, respectively, compared to the Ad-LacZ control." (PMID 17263886, 2007). "Western blotting results still showed that the PUMA protein level was increased at 12 hours and 16 hours of infection with Ad-E2F-1." (PMID 17263886, 2007). "Ad-E2F-1 infection increased PUMA promoter activity by 9.3 fold in SK-MEL-2 cells compared with the control cells infected with Ad-LacZ." (PMID 17263886, 2007). "The PUMA protein level increased at 8 hours and was still pronounced at 16 hours and 18 hours post-infection with Ad-E2F-1." (PMID 17263886, 2007). "MTT assay also showed that loss of the PUMA gene enhanced survival of HCT116 cells infected with Ad-E2F-1 compared with Ad-LacZ infection." (PMID 17263886, 2007). "The mechanism was investigated by infection with lentivirus-mediated BNIP3 or E2F1 overexpression." (PMID 36284303, 2022).
infection (continued). "Indeed, we demonstrate that E2F1 downregulation in bystander cells renders these cells more permissive to infection, by promoting Salmonella invasion, and intracellular replication." (PMID 34099666, 2021). "Infection experiments utilizing an siRNA directed against E2F1 could show that E2F1 contributes to the upregulation of FEN1 suggesting a regulation at the transcriptional level." (PMID 33770148, 2021). "HHV-6A and HHV-6B provide other examples of mislocalization coupled to cell cycle arrest, as their infection reduces E2F1-Rb complex formation and leads to accumulation of E2F1 both in the cytoplasmic and nuclear fractions, as opposed to its strict nuclear localization in normal cells." (PMID 30510918, 2018). "However, in BACEBV-GFPWT infection, the E2F1 transcript levels was seen particularly robust at 2 dpi while gradually declined to an expression level similar to uninfected PBMCs." (PMID 26908453, 2016). "Also p73 mRNA levels were lowered by shNF-YA infection, presumably as a consequence of reduced expression of E2F1, known p73 transcriptional activator." (PMID 27323853, 2016). "Chromatin immuno-precipitation (ChIP) experiments using an anti-E2F1 antibody showed that infection with wild-type GFP-EBV significantly decreases the recruitment of E2F1 to ERE1 in RPMI and two independent LCLs, while EBVΔLMP1 did not have any impact on this event in RPMI." (PMID 24809689, 2014). "We also determined the effects of endogenous CtBP1 and CtBP2 on the E2F1 promoter activity by using A549 cells that were acutely depleted of both CtBP1 and CtBP2 by infection with lentiviral vectors that express shRNAs against CtBP1 and CtBP2 followed by short term drug selection." (PMID 24955216, 2014). "Interestingly, EBNA3C knockout virus infected cells displayed a drastic increase (∼6–7 fold) in E2F1 activation compared to wild-type infection." (PMID 22438805, 2012). "However, the E2F1 transcript levels was seen particularly robust at 2 days post-infection and gradually declined to a lower expression level similar to uninfected PBMC." (PMID 22438805, 2012). "Therefore, host chromosomal changes mediated by disruption of RB/E2F1 complexes or other mechanisms of E2F1 deregulation should also be considered as possible ATM activators during infection." (PMID 21589897, 2011). "Given that E2F activity is often deregulated by infection with DNA viruses, these observations raise the possibility that an E2F1-mediated mechanism of DDR activation may be conserved among DNA viruses." (PMID 21589897, 2011). "Bax clustered and co-localized with the mitochondria after 24 hours of Ad-E2F-1 infection." (PMID 17263886, 2007). "Similarly, real-time PCR showed a 2-fold increase in PUMA expression in HCT116 PUMA+/+ cells at 6 hours after Ad-E2F-1 infection compared to cells infected with the Ad-LacZ control (data not shown)." (PMID 17263886, 2007). "Furthermore, in HCT116 PUMA-/- cells, caspase-9 activity was also increased after Ad-E2F-1 infection, albeit at a much lower level than SK-MEL-2 and HCT116 PUMA+/+ cells." (PMID 17263886, 2007). "However, in combination with Ad, the initial downregulation of E2F1 could be recovered as early as 12 h post-infection and was fully restored 36 h later, while RB protein was even further suppressed." (PMID 35948546, 2022). "In summary, we postulate that targeting E2f1, Myc, Pparγ and Stat6 in M2-like macrophages induces a shift towards immunostimulatory M1-like macrophages, which may support immune defense and hence improve therapy against infection." (PMID 32097424, 2020). "Cell cycle arrest was confirmed by the upregulation of p16 (CDKN2A), E2F1 and E2F8 after 24 h post infection with omicron." (PMID 38095608, 2023). "The levels of both E2F1 and MYC were increased in KO male mice in the presence of SP-A2 (1A0) protein rescue at the time of infection, even though most (except miR-378-3p, in KO male mice) of the miRNAs that target these genes were decreased in both sexes." (PMID 35844510, 2022).
infection (continued). "Taken together, increased expression and activities of E2F1 and FOXM1 accounted for 40% of the transcriptome induced by BKPyV-infection." (PMID 35194151, 2022). "Several transcription factors such as E2F transcription factor 1, EIF3S9, and EIF2B5, are down-regulated early in the infection and then up-regulated later in the infection." (PMID 22087245, 2011). "To address this question, we individually blocked the expression of E2F1, E2F2 or E2F3 with one of two different siRNAs prior to infection with HCMV or transduction with recombinant adenoviruses, and then scored cells for a host DDR by γH2AX immunostaining." (PMID 21589897, 2011). "Given that E2F activity is often deregulated by infection with DNA viruses including EBV, we hypothesize that E2F1 contributes to EBV induced B-cell lymphomagenesis by regulating its latent-to-lytic switch." (PMID 40773523, 2025). "Furthermore, the Rb-suppressed E2F-1 gene product accumulated to similar levels, indicating that Rb was equivalently inactivated by both UL97 and UL97-S13A during infection." (PMID 36150501, 2022). "The overwhelming majority of changed miRNAs were downregulated after infection and infection plus SP-A2 (1A0) protein rescue, and these were predicted to target genes that play a role in cell cycle and growth and proliferation pathways, such as CCND1, CCND2, CDK7, CDKN2A, E2F1, E2F2, E2F3, and MYC." (PMID 35844510, 2022). "Moreover, Ad-E2F1 significantly increased the expression of miR-15a, miR-16, and miR-29a in SaOS-2 cells, although MNNG/HOS cells showed increased expression of miR-15a and miR-16, but not miR-29a, after Ad-E2F1 infection." (PMID 27356624, 2016). "E2F1 inhibits the clearance of circulating cholesterol by regulating the expression of PCSK9, which might be related to the parasite’s critical need of cholesterol-related metabolism from Boran’s body, implicating the progressive conditions of hypocholesteraemia and hypolipidaemia after infection." (PMID 33429951, 2021).
adenocarcinoma (6 papers, 2013 to 2023). A common cancer characterized by the presence of malignant glandular cells.
metabolic disease (4 papers, 2012 to 2021). A congenital disorder (due to inherited enzyme abnormality) or acquired (due to failure of a metabolically important organ) disorder resulting from an abnormal metabolic process. "The E2F1-ELOVL2 pathway suppresses mitochondrial respiration which can be viewed as a hallmark of increased metabolic disease risk." (PMID 27631473, 2016). "Considering that ICAT is required for E2F1′s activity on pre-adipocyte differentiation, ICAT might be a therapeutic target for metabolic diseases, especially the patients with enhanced protein level of E2F1 and ICAT." (PMID 32326181, 2020). "However, it remains unknown how the transcriptional factor E2F1 interacts with regulators of pre-adipocyte differentiation and contributes to development of metabolic diseases." (PMID 32326181, 2020).
colorectal (2 papers, 2014 to 2022). "Therefore, clarification of E2F1 targets should give a clue how this versatile transcription factor family is involved in colorectal carcinogenesis." (PMID 24465681, 2014).
inflammation (2 papers, 2022 to 2023). Aberrant reaction of the microcirculation characterized by movement of fluid and leukocytes from the blood into extravascular tissues. "A prior study has attributed the alleviatory effect of miR-223-3p against inflammation diseases to targeted inhibition of E2F transcription factor 1 (E2F1)." (PMID 36093813, 2022). "The regulating function of IGF2BP1 in E2F1 and MIF expression during acute renal inflammation in vivo was then examined." (PMID 36632449, 2023).
neurological disease (2 papers, 2012 to 2025). "Ntrk3, adenylate cyclase activating polypeptide 1 receptor 1 (Adcyap1r1), E2F transcription factor 1 (E2f1) and X-ray repair in Chinese hamster cells 6 (Xrcc6) were represented within the “neurological disease” pathway." (PMID 22934110, 2012).
bacterial infection (1 paper, 2021). "A similar decrease of E2F1 levels was observed in Salmonella-infected HCT-8 cells, a colon epithelial cell line also used as a model for bacterial infection studies." (PMID 34099666, 2021).
cardiovascular diseases (1 paper, 2020). "E2F1 is the first E2F transcription factor discovered, and there are many studies on its role in cardiovascular diseases." (PMID 32420356, 2020). "Similar to E2F1, E2F2 is closely related to the function of vascular endothelial cells and cardiomyocytes, and its dysfunction may also be involved in the pathogenesis of various cardiovascular diseases." (PMID 32420356, 2020).
myopathy (1 paper, 2017). A disease of the muscle in which the muscle fibers do not function properly. "Concurrently, PGC1β up-regulates apoptosis and/or autophagy transcriptional factors such as E2f1, Atf3, Stat1, and Stat3, which may be facilitating myopathy." (PMID 28860475, 2017).
psychiatric disorder (1 paper, 2020). A disorder characterized by behavioral and/or psychological abnormalities, often accompanied by physical symptoms. "Twelve known ASD SNPs are associated with validated TF binding sites of YY1, E2F1 and USF2 enriched in neurodevelopmental and neuro-psychiatric disorder PPI network." (PMID 33080834, 2020).
E2F1 also shares sentences with these, for which no sentence is quoted: multiple myeloma (4 papers); neurodegenerative disease (4); adrenocortical carcinoma (3); colorectal adenocarcinoma (3); hyperandrogenemia (3); Malignant Brain Tumor (3); Prostatic Hyperplasia (3); psoriasis (3); acute-on-chronic liver failure (2); anaplastic thyroid cancer (2); autism (2); brain injury (2); cholangiocarcinoma (2); Cirrhosis (2); Down syndrome (2); dyslipidemia (2); Ewing sarcoma (2); non-small cell lung adenocarcinoma (2); papillary carcinoma (2); prostatic diseases (2); schizophrenia (2); tongue cancer (2); acromegaly (1); acute lymphoblastic leukemia (1); acute promyelocytic leukemia (1); allergic asthma (1); Anxiety (1); Arthritis (1); blood cancer (1); carcinosarcoma (1).
A further 60 diseases each share a sentence with E2F1 in 1 paper.